ALB (albumin)
Diseases named in the same sentence as ALB in open-access papers (continued):
Sharing a sentence is not in itself a finding about the gene and the disease.
Hypoalbuminemia (continued). "Exogenous human serum albumin supplementation can effectively improve postoperative albumin levels for patients with hypoalbuminemia after surgery." (PMID 35187165, 2022). "The results of this post hoc analysis confirmed that the administration of IV albumin is safe not only in heterogeneous ICU patients but also in ICU patients with hypoalbuminemia." (PMID 36430652, 2022). "On the other hand, we observed that more than 40% of individuals in group 1 had hypoalbuminemia (albumin < 3.5g/dL), while only one-third and one-fourth in groups 2 and 3, respectively, had albumin lower than 3.5g/dL." (PMID 36346823, 2022). "For the reasons above, the doctors were accustomed to applying the albumin infusion to increase colloidal osmotic pressure and improve hypoalbuminemia in clinical practice." (PMID 35721190, 2022). "Another mechanism of diuretic resistance in the ICU is hypoalbuminemia, which impairs furosemide delivery to the proximal tubule lumen and affects drug efficacy since furosemide is 95% bound to albumin in plasma." (PMID 37675009, 2022). "It revealed that most of the patients with infectious diseases needed red blood cell (RBC) transfusion (72.7%) and albumin (85.3%) infusion throughout the follow-up period due to anemia or hypoalbuminemia." (PMID 36117592, 2022). "The serum albumin level is a marker of nutritional status, and a level less than 35 g/L is considered to indicate hypoalbuminemia." (PMID 36072935, 2022). "Third, 13 patients in the control group underwent albumin replacement during the postoperative period because of significant hypoalbuminemia." (PMID 35160076, 2022). "First, almost all included patients (90.0% of the derivation cohort, 94.5% of the validation cohort) had hypoalbuminemia, i.e. their albumin levels were less than 3.5 g/dL." (PMID 34017041, 2021). "Short survival related to hypoalbuminemia was also reported in other studies, e.g., in peritoneal carcinomatosis, where albumin <2.8 g/dL was related to the survival <30 days." (PMID 33801869, 2021). "Hypoalbuminaemia was reported to be an important trigger factor in the elevation of fibrinogen and platelet aggregability, which can be reversed by infusing albumin." (PMID 34162417, 2021). "The use of albumin infusion for ascitic cirrhosis was definitively abandoned despite the severe hypoalbuminemia." (PMID 34281177, 2021). "Although preoperative albumin levels are predictive of postoperative complications, postoperative hypoalbuminemia occurs normally following TKA and follows a predictable postoperative course that mirrors the course of CRP." (PMID 33592030, 2021). "Hematology evidenced light anemia, leukocytosis with eosinophilia, and lymphocytosis; biochemistry and enzyme activity revealed hypoalbuminemia with decreased albumin/globulin ratio and elevated alkaline phosphatase values." (PMID 33723661, 2021). "To observe the relevant effects of exogenous albumin supplementation on the prognosis of patients with hypoalbuminemia and sepsis, we further conducted analysis on patients in the hypoalbuminemia group." (PMID 34934165, 2021). "Albumin, which is usually used later in treatment, is the favorite plasma expander, particularly when there is hypoalbuminemia." (PMID 34431837, 2021). "The average albumin level in the cohort was 3.17 g/dL (SD: 0.66 g/dL) and a total of 109 patients (60.2%) had hypoalbuminemia." (PMID 33725003, 2021). "Albumin degradation secondary to protein oxidation plays an important role in the hypoalbuminemia and increased AOPP levels of colorectal cancer patients." (PMID 34381561, 2021). "A randomized, crossover trial was performed in 65 AKI or ESKD patients with hypoalbuminemia (albumin < 3 g/dl) who required HD during hospitalization." (PMID 33407747, 2021). "The normal serum concentration of albumin in healthy adults is ≥ 4.0 g/dL, while hypoalbuminemia is defined as a serum albumin level of ≤ 3.4 g/L." (PMID 33607942, 2021).
Hypoalbuminemia (continued). "With increasing evidence of the relationship between hypoalbuminemia and poor prognosis, the prognostic value of a low albumin level has been tested and validated in several composite ratios or cumulative scores for a variety of malignancies." (PMID 33833991, 2021). "Even though serum albumin levels are widely used to determine the patient's nutritional status, in heart failure, hypoalbuminemia has been found present to a similar extent in lean, overweight, and obese patients." (PMID 34746248, 2021). "In our study, 10/12 dogs had been reported to have hypoalbuminemia [albumin <26 g/L (R.I 26.3–38.2)] with 4/12 dogs presenting severe hypoalbuminemia below 16 g/L, but free amoxicillin concentrations were not directly measured in these dogs." (PMID 34869739, 2021). "Our findings also suggest that hypoalbuminemia and lymphocytopenia (albumin and lymphocyte counts are used to calculate PNI) are important variables for predicting RRTi in sepsis patients." (PMID 34118899, 2021). "Eight patients experienced moderate to severe hypoalbuminemia, with a median albumin level of 25.8 g/L (range 13.6–35.7 g/L)." (PMID 33530944, 2021). "Among the 315 patients, 229 met the inclusion criteria, including 79 with normal albumin levels and 150 with hypoalbuminemia." (PMID 34765635, 2021). "The aim of this study is to assess the prognostic utility of serum albumin among older adults admitted for SARS-CoV-2 infection in terms of all-cause mortality and also to identify the predictors of hypoalbuminemia, such as its association with inflammation." (PMID 34768653, 2021). "Of the 88 patients, 83 (94%) had positive CRP values (>5 mg/L), 17 (19%) had hemoglobin values <10 g/dL, and 27 (31%) had hypoalbuminemia (albumin <3 g/dL) upon hospital admission." (PMID 34830694, 2021). "Owing to the reduced capacity of the liver for protein synthesis, patients with liver cirrhosis and ascites usually display reduced levels of serum albumin (hypoalbuminemia)." (PMID 34836265, 2021). "In a preliminary study, oral BCAA supplementation increased serum albumin and decreased cardiothoracic ratio in patients with HF and hypoalbuminemia." (PMID 34912870, 2021). "Serum albumin levels were reported in 23/27 cases, with all 23 patients having hypoalbuminemia; 68% (15/22) of the patients had increased serum creatinine levels; and 13 cases had anemia, with the average hemoglobin level at 103.9 ± 18.1 g/L." (PMID 35141169, 2021). "Albumin acts as an anticoagulant and antiplatelets and increases vascular permeability, which seems to explain the link between elevated D-dimer and hypoalbuminemia." (PMID 34025688, 2021). "According to univariate analysis, hypoalbuminemia (serum albumin less than 3.5 g/dL) and being in the experimental group were significantly related to anti-TB DILI." (PMID 34903999, 2021). "It is believed that the increase of albumin catabolism in hemodialysis patients induced by inflammation leads to hypoalbuminemia." (PMID 34496793, 2021). "Although patients in that study had severe hypoalbuminemia, the albumin group only received 60 g of albumin during the observation time." (PMID 34281177, 2021). "For example, inflammation is a driving force of reduced albumin levels, while hypoalbuminemia reflects the physiological stress from inflammation." (PMID 34961476, 2021). "An inverse relationship has been described between age and serum albumin, and we more frequently find older adult patients with hypoalbuminemia." (PMID 35010957, 2021). "CAD patients with hypoalbuminemia must receive medical tests including computed tomography, urine analysis and more to determine the reason for albumin decrease, and subsequently adopt effective therapy." (PMID 34961476, 2021). "SIDa and BE were significantly lower in patients with hypoalbuminemia compared to those with normal albumin levels (SIDa: 36 mmol/L vs. 39 mmol/L, P < 0.001." (PMID 34099036, 2021).
Hypoalbuminemia (continued). "The EPI-X4 precursor, human serum albumin, is used as medicinal product for many indications including hypoalbuminemia and hypovolemia." (PMID 33941197, 2021). "Ten adult client-owned dogs with hypoalbuminemia (albumin < 2 g/dL) and ongoing fluid losses were included." (PMID 34573522, 2021). "Serum albumin, creatinine, and eGFR levels were within normal limits in all children with mild pathology, whereas in the severe pathology group 48.7% had hypoalbuminemia and 23% eGFR below 90 ml/min/1.73 m2." (PMID 33089378, 2021). "Since during AKI development, kidneys start excreting albumin in urine as seen herein, hypoalbuminemia becomes more evident and a predictor of severity and death of COVID-19." (PMID 34587189, 2021). "Serum albumin is an indicator of nutritional status and hypoalbuminemia usually leads to a poor prognosis." (PMID 34001160, 2021). "Anemia was diagnosed in 122 (36.0%) patients, while 21 (6.2%) had hypoalbuminemia with serum albumin levels less than 3.5 g/dL." (PMID 34405026, 2021). "Hypoalbuminemia is defined by serum albumin <35 g/L, although clinically significant hypoalbuminemia is identified by levels <25 g/L." (PMID 35052907, 2021). "Hypoalbuminemia alters pharmacokinetics and pharmacodynamics of antimicrobial drugs, necessitating therapeutic drug monitoring and measurement of albumin serum levels, as has been recommended in guidelines for optimizing treatment." (PMID 33925831, 2021). "And the risk of postoperative complications in patients with preoperative hypoalbuminemia (serum albumin < 35g/L) was 1.89 times higher than that in patients with normal preoperative albumin(preoperative serum albumin ≥ 35g/L)." (PMID 34526075, 2021). "Among the 41 patients enrolled, 13 were undernourished with hypoalbuminemia: 9 (22.0%) presented with albumin levels <4.0 g/dL, whereas 4 (9.8%) presented with ≤3.5 g/dL." (PMID 33905438, 2021). "According to this ROC cutoff for mortality, severe hypoalbuminemia was defined as a serum albumin ≤3 g/dL." (PMID 34768653, 2021). "A recently published randomised trial of 828 hypoalbuminaemic patients with acute complications of decompensated cirrhosis randomised patients to receive daily 20% albumin infusions titrated to the degree of hypoalbuminaemia." (PMID 34419128, 2021). "In our study, the incidence and severity of hypoalbuminemia is constant across the spectrum of pH, with an albumin level of 30 g/L amounting to an alkalizing effect on the BE of approximately + 3 mmol/L." (PMID 34099036, 2021). "In this study, the incidence of hypoalbuminemia in the perioperative period was about as high as 10.31%, and albumin ≤ 28G/L was taken as the standard for grouping." (PMID 34717707, 2021). "The prognostic relevance of serum albumin in cardiovascular disorders primarily refers to hypoalbuminemia and inflammation." (PMID 34961476, 2021). "Hypoalbuminemia, i.e. albumin level less than 3.5 g/dL is reported in up to 50% of critically ill patients." (PMID 34017041, 2021). "Actually, patients with neoplastic diseases are more vulnerable to the hypoalbuminemia due to decreased albumin production from liver and increased losses in ascites or hydrothorax." (PMID 34445989, 2021). "Low levels of circulating ALB, often reaching hypoalbuminemia, is a common feature of COVID19 pathology that has been associated with worse prognosis independently of age and comorbidities." (PMID 33724185, 2021). "The first clinical trial of the nephroprotective effect of albumin infusion was achieved in patients with severe hypoalbuminemia, decompensated liver cirrhosis, and diuretic-induced fully reversible kidney injury." (PMID 34281177, 2021). "Although the albumin variable showed a statistical result (p < 0.05), the highest observed frequency was between normal albumin values, followed by hypoalbuminemia." (PMID 33669023, 2021). "The etiologies of hypoalbuminemia include malnourishment, hepatic impairment, and decreased hepatic synthesis of albumin." (PMID 34484470, 2021).
Hypoalbuminemia (continued). "At the same time, inflammation can reduce plasma albumin synthesis, resulting in hypoalbuminaemia, and thus CAR is a more sensitive predictor of inflammatory status." (PMID 33817301, 2021). "Through the subgroup analyses, this study revealed statistically significant benefits of furosemide and albumin co-administration in patients with hypoalbuminemia lower than 2.5 mg/dL or those receiving albumin doses of more than 30 g." (PMID 34851962, 2021). "Impaired liver function as indicated by hyperbilirubinemia (total bilirubin >1.2 mg/dL) and pronounced hypoalbuminemia (serum albumin <28 g/L) occurred in 17/64 (27%) and 31/58 (53%), respectively." (PMID 33572417, 2021). "Dogs with lower albumin concentrations were more likely to belong to the phenobarbital-treated group, although overt hypoalbuminemia was rarely reached." (PMID 34076758, 2021). "Patients with hypoalbuminemia were more likely to be intubated, and have pneumonia and cerebral vasospasm than patients with a normal albumin level on admission (p < 0.001)." (PMID 34765635, 2021). "In this study, concerning the impact of albumin on the calcium level, especially in patients with hypoalbuminemia, the calcium level reported was corrected for albumin [measured total calcium (mg/dl) + 0.8 × 4.0 – serum albumin (g/dl)]." (PMID 34926602, 2021). "Albumin concentrations were significantly lower in the deceased group than the recovered group, whereas hypoalbuminemia (albumin < 32 g/L) was more frequent in the deceased group." (PMID 33711813, 2021). "Our analysed cohorts differed from the total cohort in some aspects, thus potentially signalling performance bias, as albumin measurements are more frequently ordered for patients with expected hypoalbuminemia." (PMID 34921151, 2021). "More importantly, it has been shown to increase serum albumin levels among patients with hypoalbuminemia, possibly by allowing patients to increase their dietary intake of protein." (PMID 34926505, 2021). "Administering albumin in case of hypoalbuminemia was mentioned by 31 physicians (35.2%), while 37 (42%) physicians would administer crystalloid solutions or other non-albumin-based colloids." (PMID 33270161, 2021). "Our findings show a significant influence of ALB on amikacin dosage regimens: considering the same renal function, patients with hypoalbuminemia should receive higher doses than normoalbuminemic ones for warrantying a comparable treatment efficacy." (PMID 33672057, 2021). "Further investigation is warranted to demonstrate if the correction of hypoalbuminemia on admission, through methods such as intravenous albumin administration or early protein supplementation, will improve outcomes for COVID-19 patients." (PMID 33725003, 2021). "Inflammation leads to hypoalbuminaemia by reducing its half-life and synthesis and increases capillary permeability resulting in the extravasation of albumin into the extracellular space." (PMID 34138894, 2021). "This makes these patients more likely to get hypoalbuminemia which is treated primarily by the infusion of albumin." (PMID 34717707, 2021). "It is worth noting that 36% of dogs that were hypoalbuminemic at admission developed postoperative hypotension, and all dogs that developed postoperative hypotension and had postoperative albumin values measured had postoperative hypoalbuminemia." (PMID 34679039, 2021). "Human albumin (HA) is a colloid that can be used to treat hypoalbuminemia (< 35 g/L) and has been shown to increase postoperative albumin levels and reduce postoperative complications." (PMID 34717693, 2021). "The albumin level in the hypoalbuminemia group was decreased more than the control group (p < 0.001)." (PMID 34765635, 2021). "In this research, hypoproteinemia, hypoalbuminemia, hypoglobulinemia, and hypo γ globulinemia alongside a decreased albumin/globulin ratio were apparent in SS-injected rats." (PMID 34064189, 2021).
Hypoalbuminemia (continued). "Contingent on its proposed mechanism of benefit in fluid resuscitation (correction of hypoalbuminemia vs intravascular fluid expansion), studies comparing the various albumin concentrations are necessary." (PMID 33644843, 2021). "Hypoalbuminemia was present in 219/260 (84.2%) of patients, and in 71/260 (27.3%) albumin level fell under 2.5 g/dl." (PMID 34876594, 2021). "Patients with hypoalbuminemia were more likely to be intubated, and have pneumonia and cerebral vasospasm than patients with a normal albumin level on admission (43.6 vs. 8.9%, p < 0.001; 46.3 vs. 13.9%, p < 0.001; and 50.7 vs. 32.9%, p = 0.010, respectively)." (PMID 34765635, 2021). "When hs-CRP and albumin were combined, CAD patients with high hs-CRP levels (> 3 mg/L) and with hypoalbuminemia were at the highest risk of death compared with their reference group (hs-CRP ≤ 3 mg/L and albumin > 35 g/L; HR 3.79; 95% CI 1.91–7.52)." (PMID 34961476, 2021). "Synthetic colloids have been used as a substitute for albumin in patients with hypoalbuminemia with the rationale that they are capable of restoring plasma COP." (PMID 34277747, 2021). "Hyponatraemia (sodium levels < 136 mEq/L) was more frequent in patients with PO, DHF, or CS, while hypoalbuminaemia (albumin < 3.5 g/dL) was more frequent in patients with CS, RHF, or PO." (PMID 33179453, 2021). "In older adults, hypoalbuminemia can be a physiological finding, since with ageing, the serum albumin level decreases, reducing the albumin level by 20% in individuals over 70 years of age." (PMID 34768653, 2021). "This gives us a reminder for clinical work, that is, patients with RA or AS should pay more attention to nutritional status and albumin level, once hypoalbuminemia occurs, do an early intervention." (PMID 34717693, 2021). "Albumin levels were examined with a 35 g/L cut-off in a separate analysis, which found an independent relation between hypoalbuminemia and mortality (OR 2.070; CI 1.021–4.033)." (PMID 34921151, 2021). "Intravascular serum albumin level of < 35 g/L (hypoalbuminemia) has been used as an indicator of protein malnutrition, where level < 25 g/L was considered life threatening and an indication for in-hospital TPN administration." (PMID 33730334, 2021). "Given that albumin function in increasing colloidal osmotic pressure and maintaining blood volume, albumin supplementation seems to be beneficial for sepsis patients with hypoalbuminemia." (PMID 34934165, 2021). "Numerous studies have confirmed that hypoalbuminemia is an independent predictor of complications after THA and TKA, and HA administration is an effective way to improve ALB levels and correct hypoalbuminemia in a short term." (PMID 34717693, 2021). "A total of 20 children (39.2 %) with hypoalbuminemia had an average albumin value of 30.6 ± 6.4 g/L." (PMID 34753447, 2021). "The extent to which the correction of severe hypoalbuminemia with exogenous albumin can improve the impaired outcome of these patients is also part of ongoing studies." (PMID 34618163, 2021). "Based on the correlation between hypoalbuminemia and mortality, it is intriguing to investigate the value of therapeutic albumin infusions in hospitalized COVID-19 patients with severe disease." (PMID 34367693, 2021). "The finding of hypoalbuminemia should be interpreted with caution because, in inflammatory stages, albumin tends to decrease, and thereby overlap its true value." (PMID 35010957, 2021). "Secondly, albumin and pre-albumin are consistent markers of sepsis, so hypoalbuminemia was predominantly seen as patients developed septicaemia during their course of stay in ICU." (PMID 34595082, 2021). "The number of patients that consumed excessive alcohol was greater and the mean GOS on admission was lower in the hypoalbuminemia group than the normal albumin group (p < 0.001)." (PMID 34765635, 2021).